POP7 (POP7 ribonuclease P/MRP subunit)
Description:
Component of ribonuclease P, a ribonucleoprotein complex that generates mature tRNA molecules by cleaving their 5'-ends. Also a component of the MRP ribonuclease complex, which cleaves pre-rRNA sequences.
Synonyms: RPP20; RPP2; 0610037N12Rik
Tractability: PROTAC: ubiquitination databases record sites on it; its protein half-life has been measured.
Gene: Protein-coding gene on chromosome 7 (100,705,445 to 100,707,504, forward strand). Ensembl gene ENSG00000172336.
Subcellular location: Nucleus, nucleolus; Cytoplasm; Cytoplasmic granule
Subcellular location (Human Protein Atlas): Nucleoli; Vesicles
Pathways (Reactome):
Metabolism of RNA: tRNA processing in the nucleus
Gene Ontology:
Molecular function: protein binding; ribonuclease P activity; ribonuclease P RNA binding; RNA binding; nucleic acid binding
Biological process: tRNA 5'-leader removal; RNA processing; tRNA processing
Cellular component: cytoplasm; multimeric ribonuclease P complex; nucleolar ribonuclease P complex; nucleolus; ribonuclease MRP complex; nucleoplasm; nucleus
Genetic constraint (gnomAD): Loss-of-function variants: 5 observed, 8.02 expected, observed/expected ratio (o/e) 0.62, 90% interval 0.32 to 1.3. That is too few expected variants to judge how well the gene tolerates losing a copy. Missense variants: 170 observed, 200.06 expected, observed/expected ratio (o/e) 0.85, 90% interval 0.75 to 0.96. Synonymous variants: 85 observed, 86.73 expected, observed/expected ratio (o/e) 0.98, 90% interval 0.82 to 1.17.
Homologues: Orthologues: chimpanzee POP7 (100% identical), dog POP7 (99% identical), macaque POP7 (99% identical), guinea pig POP7 (98% identical), pig POP7 (98% identical), rabbit POP7 (97% identical), rat Pop7 (96% identical), mouse Pop7 (95% identical), zebrafish pop7 (69% identical), Drosophila melanogaster Rpp20 (37% identical), Caenorhabditis elegans Y62E10A.24 (30% identical).
Diseases named in the same sentence as POP7 in open-access papers:
POP7 is named in the same sentence as 10 diseases in open-access papers, as found by Europe PMC text mining. Sharing a sentence is not in itself a finding about the gene and the disease. The quoted sentences say what the papers report.
breast carcinoma (1 paper, 2022). "A recent study showed that POP7 can promote the progression of breast cancer by regulating the stability and expression of ILF3 mRNA." (PMID 36606241, 2022).
COVID-19 (1 paper, 2021). A disease caused by infection with severe acute respiratory syndrome coronavirus 2. "Meanwhile, according to the results of LFA performed with 12 COVID-19-positive samples, 11 samples were positive with clear positive lines for T1, T2, and POP7." (PMID 34562891, 2021). "One of the samples was considered a presumptive positive as the COVID-19-specific T1 was inconclusive whereas it was positive for T2 and POP7." (PMID 34562891, 2021). "We considered that the sample was COVID-19 positive when the tests showed positive signals for both SARS-CoV-2-specific targets, T1 and T2, and for the POP7 target of RNase P. Fluorescence signal was considered positive or negative in comparison to the background noise." (PMID 34562891, 2021).
esophageal cancer (1 paper, 2021). A primary or metastatic malignant neoplasm involving the esophagus. "Survival analysis reveals that a higher expression of CLK1 predicts a significant worse prognosis, and a lower expression of POP7 predicts a worse prognosis in esophageal cancer." (PMID 34568328, 2021). "Survival analysis showed that the higher the expression of CLK1 in esophageal cancer tissues is, the worse the prognosis of patients; the lower the expression of POP7 is, the worse the prognosis of patients." (PMID 34568328, 2021). "Our focus was on the expression of CLK1 and POP7 in esophageal cancer." (PMID 34568328, 2021). "First, the expressions of CLK1 and POP7 were compared in 28 pairs of primary esophageal cancer and non-cancerous tissues from the cDNA array." (PMID 34568328, 2021). "Consistent with our previous results, compared with non-cancerous tissues, CLK1 mRNA levels are lower in esophageal cancer, and POP7 mRNA levels are higher." (PMID 34568328, 2021). "No research studied the relationship between POP7 and esophageal cancer." (PMID 34568328, 2021). "Our results show that the level of POP7 mRNA in esophageal cancer is relatively higher, and the lower expression of CLK1 is, the worse prognosis of patients in esophageal cancer, suggesting that POP7 may play a role in promoting progression of esophageal cancer." (PMID 34568328, 2021).
retinitis pigmentosa (1 paper, 2021). Retinitis pigmentosa (RP) is an inherited retinal dystrophy leading to progressive loss of the photoreceptors and retinal pigment epithelium and resulting in blindness usually after several decades. "Studies have found that POP7-related diseases include retinitis pigmentosa and hairy tongue." (PMID 34568328, 2021).
virus infection (1 paper, 2024). "The knockdown of POP7 notably restricted the infection with RBSDV in SBPH; however, whether POP7 modulates the viral infection in host insects via involvement in the RNA processing pathway and the processing of capped intron-containing pre-mRNA pathway remains unknown." (PMID 38257797, 2024).
infection (1 paper, 2024). The state of being infected such as from the introduction of a foreign agent such as serum, vaccine, antigenic substance or organism. "As such, POP7 in SBPH might interact with such proteins to modulate infection with RBSDV." (PMID 38257797, 2024). "Ls-miR750-3p interacts with the POP7-specific 3′-UTR sequence from 716 to 740, but does not bind another sequence from 128 to 147 to modulate RBSDV infection." (PMID 38257797, 2024).
POP7 also shares sentences with these, for which no sentence is quoted: tumor (2 papers); Arthritis (1); cancer (1); esophageal squamous cell carcinoma (1).